METTL2B (methyltransferase 2B, tRNA N3-cytidine)
Description:
S-adenosyl-L-methionine-dependent methyltransferase that mediates N(3)-methylcytidine modification of residue 32 of the tRNA anticodon loop of tRNA(Thr)(UGU) and tRNA(Arg)(CCU).
Synonyms: METL; FLJ11350; METTL2; PSENIP1
Tractability: PROTAC: ubiquitination databases record sites on it.
Gene: Protein-coding gene on chromosome 7 (128,476,729 to 128,506,602, forward strand). Ensembl gene ENSG00000165055.
Subcellular location: Cytoplasm
Gene Ontology:
Molecular function: protein binding; tRNA (cytidine) methyltransferase activity; tRNA (cytidine-3-)-methyltransferase activity; RNA methyltransferase activity; S-adenosylmethionine-dependent methyltransferase activity
Biological process: tRNA metabolic process; tRNA methylation
Cellular component: cytoplasm
Genetic constraint (gnomAD): Loss-of-function variants: 26 observed, 45.54 expected, observed/expected ratio (o/e) 0.57, 90% interval 0.42 to 0.79. The upper end of that interval is the gene's LOEUF score, 0.79, which puts it in group 3 of 6, group 1 being the genes least tolerant of losing a copy. Missense variants: 306 observed, 439.31 expected, observed/expected ratio (o/e) 0.7, 90% interval 0.63 to 0.77. Synonymous variants: 126 observed, 158.9 expected, observed/expected ratio (o/e) 0.79, 90% interval 0.69 to 0.92.
Homologues: Orthologues: chimpanzee METTL2B (99% identical), chimpanzee METTL2B (95% identical), dog METTL2A (89% identical), rat Mettl2 (80% identical), mouse Mettl2 (79% identical), zebrafish mettl2a (63% identical), tropical clawed frog mettl2b (60% identical). Paralogues in human: METTL2A (98% identical), METTL8 (51% identical), METTL6 (32% identical).
Diseases named in the same sentence as METTL2B in open-access papers:
METTL2B is named in the same sentence as 13 diseases in open-access papers, as found by Europe PMC text mining. Sharing a sentence is not in itself a finding about the gene and the disease. The quoted sentences say what the papers report.
gastric cancer (1 paper, 2024). A primary or metastatic malignant neoplasm involving the stomach. "Furthermore, an additional study demonstrated that METTL2B serves as a prominent biomarker in gastric cancer and exhibits a strong correlation with unfavorable prognosis, thereby indicating the potential of METTL2B for assessing cancer progression." (PMID 39019857, 2024).
glioma (1 paper, 2024). A benign or malignant brain and spinal cord tumor that arises from glial cells (astrocytes, oligodendrocytes, ependymal cells). "We observed the high expression levels of METLL8, METLL2A, TRMT112, METTL2B, GTPBP3, METTL6, and NSUN4 in cells in the S, G2M, and G1 phases, which were similar for astrocytes, glioma cells, and oligodendrocytes." (PMID 38824202, 2024).
ovarian serous cystadenocarcinoma (1 paper, 2022). A malignant serous cystic epithelial neoplasm arising from the ovary. "The top three cancer types with genetic alteration of METTL2B is Uterine Corpus Endometrial Carcinoma (5%), Skin Cutaneous Melanoma (2%), and Ovarian serous cystadenocarcinoma (4%)." (PMID 36266694, 2022).
ovarian tumor (1 paper, 2026). "In lymphocytes, METTL2B promotes YTHDF2-mediated decay of cytotoxic effector transcripts such as perforin and granzyme B 115, whereas in ovarian tumor cells, METTL2B stabilizes DNA repair factors including BRCA1 and FANCD2 via IGF2BP3-dependent mRNA protection." (PMID 41362736, 2026).
Pan (1 paper, 2021). "We found that, similar to the TCGA Pan-Cancer cohort, at least ten METTLs (e.g. METTL1, METTL2A, METTL2B, EEF1AKNMT) showed high-level amplifications in more than 2% of CCLE lines." (PMID 34285249, 2021).
Thyroid carcinoma (1 paper, 2022). "In contrast, there was down-regulation of these four genes in Kidney Chromophobe (KICH), Kidney renal clear cell carcinoma (KIRC), and Thyroid carcinoma Compared to METTL8, the other three genes (METTL2A, METTL2B and METTL6) exhibited a more homogenized co-expression in various cancer types." (PMID 36266694, 2022).
tumor (5 papers, 2022 to 2026). "Single-cell transcriptomic profiling reveals spatial co-distribution of METTL2B-overexpressing tumor cells with exhausted CD8+ T cell clusters, demonstrating microenvironmental co-evolution driven by epitranscriptomic crosstalk." (PMID 41362736, 2026). "METTL2B overexpression in tumor-infiltrating leukocytes simultaneously suppresses antitumor immunity and enhances platinum sensitivity through cell-type-specific RNA stability regulation." (PMID 41362736, 2026). "This means suppressing METTL2B activity in immune cells to restore cytotoxicity, while transiently enhancing METTL2B function in tumor cells to exacerbate platinum-induced DNA damage." (PMID 41362736, 2026). "Interestingly, expression of METTL2A, METTL2B, and METTL6 mRNA is elevated in most tumor types compared with corresponding normal tissues and is associated with poor prognosis." (PMID 38982125, 2024). "The differential expression analysis of METTL2A, METTL2B METTL6 and METTL8 was conducted between tumor tissue and normal tissue in 24 different cancer types." (PMID 36266694, 2022).
cancer (4 papers, 2021 to 2025). A tumor composed of atypical neoplastic, often pleomorphic cells that invade other tissues. "The m3C associated genes showed aberrant expression in 17 cancer types for METTL2A, 15 cancer types for METTL2B, 14 cancer types for METTL6 and 13 cancer types for METTL8." (PMID 36266694, 2022). "Of the 30 METTLs, expressions of eight (METTL1, METTL7B, METTL5, NTMT1, METTL2A, METTL2B, EEF1AKNMT, METTL6) were significantly (FDR < 0.05) associated with unfavorable overall survival across cancers." (PMID 34285249, 2021). "We identified a subset of METTL genes, notably METTL1, METTL2A, METTL2B, METTL7B, NTMT1, and METTL26, with high frequencies of genomic amplification and/or up-regulation, while METTL7A and METTL24 were under-expressed, at both mRNA and/or protein levels in a spectrum of human cancers." (PMID 34285249, 2021). "In this study, we found that several METTLs, such as METTL2A, METTL2B, and METTL26, which have not been previously investigated systematically, are upregulated at mRNA and protein levels in a subset of human cancers compared to normal tissue." (PMID 34285249, 2021).
METTL2B also shares sentences with these, for which no sentence is quoted: infection (2 papers); developmental delay (1); renal carcinoma (1); Skin Cutaneous Melanoma (1); uterine corpus endometrial carcinoma (1).